BDNF (brain derived neurotrophic factor)
Diseases named in the same sentence as BDNF in open-access papers (continued):
Sharing a sentence is not in itself a finding about the gene and the disease.
cognitive decline (continued). "Enhanced level of CCL2 in CSF correlates with cognitive decline and IL-8 production by neurons is related to formation of brain-derived neurotrophic factor (BDNF)." (PMID 34572312, 2021). "In this context, research efforts have sought to assess the value of serum BDNF levels, which are correlated with BDNF expression in the brain, and improve our understanding of age-related cognitive decline." (PMID 34239422, 2021). "Exenatide improved age-dependent cognitive decline through promoting the BDNF-TrkB neurotrophic axis and inhibiting apoptosis by activating decreasing p75NTR-mediated signaling." (PMID 34108878, 2021). "L. plantarum C29 improved cognitive function in mice and patient with mild cognitive decline by regulating NF-κB activation and inducing BDNF expression." (PMID 32158447, 2020). "Previous studies in MDD patients have found correlations between BDNF levels and the presence of melancholic features and psychomotor retardation, DE severity and duration, and cognitive decline during performances of TMT-B and verbal delayed recall." (PMID 32922315, 2020). "It is worth noting that in neurodegeneration, an impairment of brain-derived neurotrophic factor (BDNF) occurs, paralleled by cognitive decline and decrease of synaptic plasticity and memory loss." (PMID 33375429, 2020). "Series of studies have shown that miR-206 is highly expressed in the brain of AD patients or AD animal models, which contribute to cognitive decline by inhibiting BDNF expression." (PMID 32460803, 2020). "IL-1β can suppress BDNF-dependent synaptic plasticity and cognitive decline through disturbing the BDNF signaling pathway." (PMID 32425784, 2020). "When starved, the expression of brain-derived neurotrophic factor is promoted which in turn shifts brain metabolism, is trophic to the brain, and anti-inflammatory therefore, potentially aiding with age related cognitive decline." (PMID 31827790, 2019). "Luteolin increased the levels of brain-derived neurotrophic factor (BDNF) and improved oxidative stress-mediated cognitive decline." (PMID 31565046, 2019). "In conclusion, several environmental and lifestyle interventions that reduce age-dependent cognitive decline and pathological degeneration can also increase BDNF production, suggesting that BDNF is neuroprotective." (PMID 31440144, 2019). "In vivo studies using transgenic mice supported the positive effect of intranasal-injected BDNF on cognitive decline." (PMID 30355327, 2018). "In particular, the BDNF polymorphism resulting in a Val66Met substitution, which reduces the activity-dependent neuronal secretion of BDNF, accounts for up to 30% of the variability in cognitive decline in AD patients." (PMID 29520217, 2018). "With the help of BDNF treatment, deposition of Aβ in the brain was restrained and the cognitive decline was postponed in APP/PS1transgenic mice." (PMID 29937713, 2018). "Since BDNF counteracted the effects of the Aβ1−42 oligomers on neuronal apoptosis, we next sought to determine the roles of BDNF in the aggregation of Aβ and the cognitive decline of the APP/PS1 Tg mice." (PMID 28377712, 2017). "A reduction of brain BDNF expression was demonstrated to correlate with the degree of cognitive decline not only in AD, but also in subjects with mild cognitive impairment, in older adults and in the “oldest-old”." (PMID 29249935, 2017). "Blocking BDNF signaling with anti-TrkB antibodies induces cognitive decline in exercise animal models." (PMID 28377712, 2017). "For that, a systematic review was applied exploring studies using exercise interventions to evaluate changes in parameters of EF and reporting measures of BDNF for aging individuals undergoing processes of cognitive decline." (PMID 28469588, 2017).
cognitive decline (continued). "The genes selected for investigation included genetic polymorphisms with well-described influences on cognitive function, brain plasticity, and risk of ageing-related cognitive decline (APOE, BDNF Val66Met, KIBRA, COMT Val158Met, SERT 5-HTTLPR)." (PMID 30631459, 2017). "In our study, BDNF played pivotal roles in suppressing the deposition of Aβ and reducing cognitive decline of the APP/PS1 Tg mice." (PMID 28377712, 2017). "Although peripheral BDNF level was found to potentially act as protective factor for cognitive decline, the optimum level of peripheral BDNF is yet to be determined." (PMID 29109736, 2017). "Therefore, reduction of BDNF could also be a risk factor for cognitive decline." (PMID 29109736, 2017). "The overexpression of BDNF in the hippocampus mimics the beneficial effect of curcumin on cognitive decline in the AD model." (PMID 26114940, 2015). "Literature reports have shown a decrease in BDNF serum levels to negatively correlate with cognitive decline and deficits in LTP and memory in dogs." (PMID 26464952, 2015). "A recent report examining BDNF and cognitive decline from the Health ABC study suggests that in older women (mean age 74.9 years) BDNF levels differ by race." (PMID 26161003, 2015). "Given the role of BDNF in regulating synaptic plasticity, the present findings give further support to the hypothesis that this trophic factor may be a potential biomarker for evaluating cognitive changes in PD and other neurological syndromes associated with cognitive decline." (PMID 26441580, 2015). "Studies have shown that individuals with AD exhibit a stage-dependent reduction of serum BDNF levels, with reductions significantly correlating with the cognitive decline." (PMID 24764190, 2014). "Brain-derived neurotrophic factor (BDNF) links learning, memory and cognitive decline in elderly, but evidence linking BDNF allele variation, cognition and brain structural differences is lacking." (PMID 24465375, 2014). "A second caveat is that we only investigated indirect interactions between APOE, BDNF Val66Met, Aβ and cognitive decline in adults with aMCI." (PMID 24475133, 2014). "The relevance of these findings to the role of BDNF misexpression in mood disorders and cognitive decline is discussed." (PMID 22265241, 2012). "In addition, increased levels of inflammatory markers like IL-1β, IL-12, TNF-α, CRP, low CSF and serum BDNF, and altered adipokines are observed in individuals exhibiting both cognitive decline and depressive symptoms." (PMID 40807098, 2025). "Nonetheless, in our study, diagnostic accuracy of α-klotho, IL-6, TNF-α, and BDNF is low, and there is no statistical difference between the cognitive decline and cognitive undiminished groups." (PMID 40950978, 2025). "Second, we only briefly mentioned BDNF, glutamate excitotoxicity, and oxidative stress/mitochondrial dysfunction, each of which significantly influences pain sensitivity (e.g., neuropathic pain), inflammation, and cognitive decline." (PMID 41373439, 2025). "Meanwhile chronic hyperglycaemia, insulin resistance and low grade inflammation damage the cerebral microvasculature, reduce BDNF levels, and through oxidative stress and advanced glycation end products promote Aβ accumulation and tau hyper phosphorylation, thereby accelerating cognitive decline." (PMID 41460428, 2025). "Post-mortem analyses indicate that higher BDNF expression levels, as measured in regions such as the dorsolateral prefrontal cortex (DLPFC), are associated with significantly slower rates of cognitive decline and a reduced burden of amyloid and tau pathology across multiple cortical regions." (PMID 41302511, 2025). "A negative correlation has been shown between DPP-4 activity and BDNF levels in elderly individuals, indicating that higher DPP-4 activity could lead to lower BDNF and increased cognitive decline." (PMID 39904872, 2025).
cognitive decline (continued). "Studies have also shown a link between low BDNF levels and cognitive decline in people with cancer." (PMID 41155494, 2025). "This shows that having the BDNF Met allele may prevent compensatory brain mechanisms in people with the APOE E4 gene, resulting in accelerated age-related brain changes and cognitive decline." (PMID 40360788, 2025). "We also highlight how BFRE might be applied as a safe and effective strategy to enhance BDNF, thereby supporting brain health and potentially protecting against cognitive decline with aging." (PMID 40757562, 2025). "An excellent diagnostic accuracy of plasma biomarkers of Aβ and tau obtained with ultrasensitive techniques has recently been demonstrated, and other potential blood biomarkers, including NfL, GFAP, BDNF are of particular interest in the early stages of cognitive decline." (PMID 40400914, 2025). "Importantly, BDNF plasma levels significantly increase with physical exercise, further supporting the role of exercise therapy in the prevention of cognitive decline." (PMID 40400914, 2025). "Reduced serum BDNF levels are specifically linked to rapid cognitive decline in AD, rather than gradual cognitive decline." (PMID 40709526, 2025). "Notably, obese individuals tend to exhibit lower BDNF levels, potentially contributing to cognitive decline." (PMID 38785805, 2024). "Interestingly, expression of both LH and BDNF are known to be increased in SLE patients and are also known to participate in cognitive decline through loss of memory most likely associated with the hippocampus." (PMID 39014006, 2024). "Investigating the intricate relationship between BDNF and GCs in AD remains an active area of research, offering hope for novel interventions aimed at mitigating cognitive decline and improving the lives of individuals affected by this challenging neurodegenerative disorder." (PMID 38338875, 2024). "The primary mechanisms by which obesity may lead to cognitive decline include down-regulation of BDNF/TrkA signaling, increased neuro-inflammation and oxidative stress, neurovascular uncoupling, and weakened BBB integrity." (PMID 39457698, 2024). "Furthermore, exercise increases the level of BDNF according to previous studies, and BDNF functions with exercise to promote hippocampal neurogenesis and improve cognitive decline in mice." (PMID 38110646, 2024). "Omega-3 supplementation has shown promise in delaying cognitive decline and neurodegeneration, potentially due to its anti-inflammatory and antioxidative properties, as well as its role in neurogenesis and brain-derived neurotrophic factor (BDNF) enhancement." (PMID 39596544, 2024). "In the aging brain, there tends to be an imbalance between proBDNF and mature BDNF levels, with an increase in the ratio of proBDNF to mature BDNF, a pathogenic process which is thought to contribute to aging-related cognitive decline and neuronal dysfunction." (PMID 39656488, 2024). "Moreover, riluzole (RZ)-mediated increased BDNF in vivo in the chemotherapy-exposed mice reversed cognitive decline." (PMID 39696694, 2024). "BDNF expression and function is affected during aging in various ways, which may contribute to cognitive decline and neurodegeneration." (PMID 39194496, 2024). "Higher BDNF expression can delay cognitive decline and impede the pathological progression of AD." (PMID 39648181, 2024). "In addition, patients with cognitive decline have significantly lower plasma BDNF concentrations than cognitively unchanged patients." (PMID 38559694, 2024). "Additionally, BDNF was shown to prevent lesion-induced death of entorhinal cortical neurons in rats and adult primates, while reversing neuronal atrophy and improving cognitive decline in aged primates." (PMID 39935805, 2024). "However, if downregulation of BDNF by tau was the driver of cognitive decline and neurodegeneration observed in clinical studies, human Met66 carriers and Val66 homozygotes should show equivalent increases in CSF tau in early AD." (PMID 38454193, 2024).
cognitive decline (continued). "This suggests that BDNF released by platelets may have a protective effect against cognitive decline." (PMID 39568824, 2024). "The indirect effect of skeletal muscle on cognitive decline through BDNF." (PMID 38559694, 2024). "Some significant observations of the current study are the fact that the PCNA and BDNF expression in the MP groups increased, which suggests the presence of DNA lesions and a possible cognitive decline, whereas in terms of inflammation, it was present in all groups besides the control." (PMID 39125900, 2024). "Moreover, BDNF infusion in aged rats reversed cognitive decline and improved age-related gene expression disruptions." (PMID 39935805, 2024). "Therefore, BDNF had a partial direct effect on cognitive decline, and the contribution rates of the intermediary effect to the total effect were 21%, 19.7%, 35%, and 20.7% for SLM, SMM, SMI, and FFM, respectively." (PMID 38559694, 2024). "NK109 and its supplement NS may improve cognitive decline, neuroinflammation, and gut inflammation by modulating NF-κB-mediated BDNF expression and gut microbiota." (PMID 36771498, 2023). "Aging is associated with low levels of BDNF, suggesting that maintaining adequate levels of BDNF could help prevent or delay the onset of cognitive decline." (PMID 38004014, 2023). "The potential retarding effect of BDNF on the rate of cognitive decline may be a consequence of its neuroprotective effects in the brain." (PMID 36969561, 2023). "We observed that insomnia, rather than cognitive decline, is significantly associated with BDNF concentration, and these effects are independent of other variables." (PMID 37108547, 2023). "Since the results demonstrate that the proBDNF content decreases in insomnia alone, cognitive decline alone, and in their combination, we aim to measure whether BDNF (the active form of the neurotrophin) concentration was also altered by insomnia." (PMID 37108547, 2023). "Given its potential functional and epigenetic effects, we hypothesize that butyrate protects against neurotoxin QA–induced cognitive decline through mechanisms of epigenetic regulation of BDNF and promotion of neurite outgrowth." (PMID 36787221, 2023). "After controlling for all variables in the model, including insomnia and cognitive decline, we observed that insomnia is negatively associated with BDNF concentration (β = −1899.98, p < 0.01), whereas cognitive decline was not significant." (PMID 37108547, 2023). "Exercise-induced PGC-1α was accompanied by an increase in BDNF release, indicating that swimming exercise could ameliorate cognitive decline through SIRT1/PGC-1α/BDNF." (PMID 36999158, 2023). "Hence, in the present study, we quantified pro-BDNF (inactive) and BDNF (active) concentrations in serum samples derived from older individuals with insomnia and/or cognitive decline." (PMID 37108547, 2023). "The results from the ELISA assay showed that individuals with insomnia alone (Group 2), or with the combination of insomnia and cognitive decline (Group 4) had significantly decreased BDNF concentrations as compared to controls (p = 0.0029; p = 0.0051, respectively)." (PMID 37108547, 2023). "This study also aimed to investigate the association between cognitive decline and plasma BDNF concentrations in patients diagnosed with AD and MCI and to assess if plasma BDNF concentrations might be used as a biomarker of cognitive decline." (PMID 36979505, 2023). "Therefore, the long-term administration of BWF suppresses cognitive decline by increasing hippocampal BDNF production in SAMP8 mice." (PMID 35807886, 2022). "Kaempferol can improve the cognitive decline in AD mice induced by intracerebral injection of Aβ1-42, which may be related to a reduction in oxidative stress and enhancement in the BDNF/TrkB/CREB signaling pathway." (PMID 35646138, 2022).
cognitive decline (continued). "Several studies of streptozotocin-induced diabetic animal model indicated that cognitive decline with downregulation of BDNF and Bcl2 expressions in the hippocampus, BDNF and CREB expressions in the hippocampus, and BDNF and pTrkB levels in the cerebral cortex." (PMID 35743182, 2022). "The BDNF Val/Val genotype in Parkinson’s disease leads to a set of cortical and subcortical brain alterations that could promote cognitive decline." (PMID 35743271, 2022). "Taken together, these results suggested the possibility that preoperative resistance training may ameliorate laparotomy-induced cognitive decline through inducing myokines and the subsequent BDNF/Akt signaling in the hippocampus of aged mice." (PMID 35705955, 2022). "Therefore, hsa-miR-664a-3p was upregulated in AD patients, which downregulated CREB1 and BDNF expression levels, thereby leading to a cognitive decline in AD patients." (PMID 36040555, 2022). "Therefore, an alteration of BDNF/TrkB signaling with aging and/or pathological conditions has been indicated as a potential mechanism of cognitive decline." (PMID 35887075, 2022). "However, the pre-aspects of cognitive decline like blood perfusion to the brain, effects on the working memory and presence of BDNF in serum were discussed." (PMID 36429835, 2022). "Higher BDNF expression is associated with slower cognitive decline in both non-demented and AD older subjects." (PMID 36552799, 2022). "Based on these observations, we hypothesize that increased NAD+/NADH levels as well as BDNF could possibly slow down cognitive decline or aging related diseases through the stimulation of DNA repair pathways and the consequent lowered oxidative stress." (PMID 35585026, 2022). "Lower serum levels in AD could be mainly due to both the toxic effects of Aβ accumulation and the reduced physical activity accompanying cognitive decline, as BDNF expression in the hippocampus is increased by exercise." (PMID 36498925, 2022). "The presence of the Met-allele in the brain-derived neurotrophic factor (BDNF) genotype was associated with an decreased hippocampal volume in young adults and an increased rate of cognitive decline in middle aged adults in episodic memory and executive functions across more than 6 years." (PMID 35962371, 2022). "These benefits may be mediated by various molecules released during physical exercise such as BDNF which enhances learning, and prevents cognitive decline." (PMID 35619926, 2022). "Telmisartan may also protect against cognitive decline by means of tropomyosin-related kinase B and brain-derived neurotrophic factor up-regulation in the hippocampus." (PMID 34280191, 2021). "Other side-effects such as cognitive decline, visual hallucinations and daytime sleepiness have been implicated in various polymorphisms of the COMT, DRD2, DRD3, HOMER1 and BDNF genes, but lack consistency in the results to consider current clinical implementations." (PMID 34281267, 2021). "First, because of the cross-sectional design of the study, it is not possible to infer a direction or a causal link between BDNF levels, platelet markers and cognitive decline." (PMID 34557534, 2021). "Apathy, which is manifested by cognitive decline, may lead to a reduction in exercise and contribute to lower serum BDNF levels." (PMID 33967943, 2021). "However, the decrease in the levels of BDNF and 3-NT seems to trigger cognitive decline in patients with low education levels because their low cognitive reserve prevents them from compensating for organ damage derived from alcohol consumption." (PMID 34341419, 2021).